EGF (epidermal growth factor)
Diseases named in the same sentence as EGF in open-access papers (continued):
Sharing a sentence is not in itself a finding about the gene and the disease.
infection (continued). "Further, we found that EGF treatment induces gene expression changes in B. burgdorferi reminiscent of later stages of host infection." (PMID 38876107, 2024). "That is, the combination of recombinant epidermal growth factor and nanosilver dressings can effectively promote DFUs’ wound healing and prevent infection." (PMID 37124747, 2023). "Cells treated with both EGF and virus had an additive effect to the number of filopodia, and there was an additive 88% increase in infection when the drug was added with virus simultaneously." (PMID 35746622, 2022). "It is notable that infection levels in the presence of bradykinin or EGF were higher than in the presence of virus alone." (PMID 35746622, 2022). "Their synergistic effects on inflammation and infection suggest that EGF and DOX can be utilized as adjuvants in treating DWs with infections." (PMID 36661795, 2022). "The percentage of infection was evaluated for cells treated with bradykinin and EGF via flow cytometry (FF)." (PMID 35746622, 2022). "Our data show an additive effect in filopodia numbers when EGF and virus are added and this resulted in a statistically significant increase in infection." (PMID 35746622, 2022). "After waiting for 48 h after lentiviral infection with shRNA coding particles, VSMCs were stimulated with AngII or EGF, apart from a control group treated with the vehicle." (PMID 34944046, 2021). "EGF is beneficial in protecting neonates against pathogen infection by enhancing neonatal intestinal development." (PMID 33668322, 2021). "In contrast, IL-4, IL-5, IL-6, and epidermal growth factor (EGF) reached peak levels late during infection, between 15 and 25 DPI, before dropping considerably at the terminal time point." (PMID 33436428, 2021). "Our studies established that parasitic wasp pathogen infection induces ROS in the niche cells, resulting in the secretion of the epidermal growth factor (EGF) cytokine signal." (PMID 34422833, 2021). "The results of the study showed that a Bb infection of HUVECs induced expression of epidermal growth factor (EGF) which, in turn, significantly enhanced cell proliferation in vitro." (PMID 32302357, 2020). "A previous study reported that EGF was significantly higher in healthy patients compared to pH1N1 infection and the authors suggested that EGF was actively suppressed, in an effort to protect the lung from host or virus mediated damage." (PMID 33202895, 2020). "In this study, we determined that active infection of human umbilical vein endothelial cells (HUVECs) by live Bb induced host cell secretion of epidermal growth factor (EGF) using ELISA." (PMID 32302357, 2020). "In this study, EGF production by 24-h infected HUVECs was ~5-fold greater than uninfected cells when Bb strain LSS001 was used in infection and ~7-fold and significantly greater when Bb strains LSS100 or LSS500 were used (P < 0.05)." (PMID 32302357, 2020). "As observed with EGF production levels, the mitogenic response was significantly greater during infection by LSS100 vs. LSS001, suggesting a possible role for GroEL in HUVEC proliferation, perhaps by enhancing bacterial resistance to intracellular stress." (PMID 32302357, 2020). "In primary human hepatocytes, 2 ng/ml of EGF enhanced HBV infection in the FBS-free condition and the infection was gradually reduced over 5 ng/ml of EGF." (PMID 32873852, 2020). "To further analyze the inhibition of both AKT and MEK1/2 pathways by CMV, we monitored their responsiveness to EGF over a time course of infection." (PMID 31725811, 2019). "For example, EGF increases the infection rate of ADAM17-depleted cells, EGF increases the proximity between L1 and CD151 after ADAM17 knockdown, and ADAM17 knockdown diminishes the overlap between L1 and EGFR." (PMID 31107240, 2019). "With this in mind, we conducted a second set of experiments where GPA hFIBs were grown following infection in serum-free medium (SFM) containing both EGF and RA." (PMID 29979748, 2018).
infection (continued). "We found EGF as the most significantly down-regulated gene after 4 days of infection which its expression was 5.8 times reduced." (PMID 30024933, 2018). "Previous studies in neonatal pigs infected with RV already pointed to a beneficial role of high physiological levels of EGF in stimulating recovery of epithelium in the small intestine following infection." (PMID 28558652, 2017). "The disruption in the normal homeostasis of mucosa would induce the production of EGF, also expressed in the submandibular salivary glands, in order to restore the integrity of mucosa after infection." (PMID 28558652, 2017). "The internalization of EGFR following EGF stimulation in UL135STOP infection reflected that of WT infection at the early time points, marked by early oscillation in EGFR surface levels." (PMID 27218650, 2016). "Whereas, co-stimulation with EGF after HB101 infection caused an increment of ERK1/2 phosphorylation at 100% at the different infection times tested, similar to those levels induced by the positive EGF control." (PMID 27774437, 2016). "Whereas pre-treatment with either UO126 (12.5 μM) or SB202190 (20 μM) prior to infection successfully inhibited the EGF and W. chondrophila induced phosphorylation of p42/44 and p38 MAPK." (PMID 27002636, 2016). "The differences in EGFR trafficking are summarized by plotting EGFR surface levels (relative to levels prior to EGF stimulation in each infection) at 1, 10, 25 and 60 minutes." (PMID 27218650, 2016). "Three days after infection, infected cells were transferred onto a coated dish for 1 day and then cultured in NM containing 20 ng/mL bFGF and 20 ng/mL EGF for more than 17 days." (PMID 24991651, 2014). "Anti-inflammatory nanosilver combines with EGF to create a sustained-release carrier that has resistance to infection and sustained-release properties similar to those of EGF." (PMID 23596495, 2013). "The anti-dpERK staining observed following infection was comparable to the levels observed when the EGF pathway was autonomously activated in the gastric stem cell population." (PMID 24236188, 2013). "The results showed that in AGS cell treated with EGF, Thr286 phosphorylation of CaMKIIα increased by nearly 2.5 folds and infection with Ad-PKG II and treatment with 8-pCPT-cGMP inhibited the increase of the phosphorylation induced by EGF." (PMID 23613900, 2013). "The conditional esgts driver line was first used to block EGF signaling and flies were then subjected to Pe infection." (PMID 24236188, 2013). "Pre-infection with Ad-PKG II and treatment with 8-pCPT-cGMP reversed the effect of EGF, causing a marked decrease in Bcl-2 expression." (PMID 24273605, 2013). "EGF was able to fully restore infection levels but KGF at the same concentrations was only able to partially restore infection levels to those seen in CM." (PMID 22346752, 2012). "After infection, the cells were cultured in defined conditions with epidermal growth factor (EGF) to promote transdifferentiation and were found to have an active endogenous insulin gene." (PMID 22761608, 2012). "Depletion of syndecan-1 or epidermal growth factor and removal of serum factors reduce infection, while replenishment of growth factors restores infection." (PMID 22346752, 2012). "HPV particles associate with GFRs at the keratinocyte plasma membrane and the removal of syndecan-1 HSPG or EGF inhibits infection." (PMID 22346752, 2012). "Control experiments were also carried out in which wortmannin was added to cells for 30 min or 3 hr prior to infection with Salmonella or EGF treatment." (PMID 21779406, 2011). "The same experimental protocol was used but cells were additionally stimulated with EGF for 5 min at the end of the 2-hour infection, prior to collection of cellular material and western blot analysis (right panel-)." (PMID 19718432, 2009). "Altogether, these data demonstrate that hPIV3 infection or hPIV3-C expression alone both enhance MAPK/ERK pathway activation in EGF-stimulated cells." (PMID 19806178, 2009).
infection (continued). "Our data now clearly show that vaccinia virus stimulates the EGF signalling pathway to enhance cell survival during infection." (PMID 19388902, 2009). "In contrast, by 72 hr post-infection nuclear BrdU incorporation was shown to be minimal in parasite-infected cells where increases in incorporation were found to be refractory to EGF stimulation (72 hr)." (PMID 19480704, 2009). "The expression of CA-Akt inhibited lactogenic differentiation of HC11 cells, and the infection with DN-Akt adenovirus enhanced β-casein transcription and rescued β-casein promotor-regulated luciferase activity in the presence of EGF." (PMID 16984645, 2006). "Additional options include topical biologics (eg, epidermal growth factor, granulocyte macrophage colony stimulating factor), corticosteroids, and silver-based dressings, which help reduce inflammation, promote tissue repair, and prevent infection." (PMID 40661110, 2025). "Infection with P. aeruginosa (PA14) activates the extracellular signal-regulated kinase (ERK) pathway by upregulating the expression of the epidermal growth factor (EGF) ligand gene lin-3." (PMID 40180610, 2025). "We discovered infection-induced hepatic expression of EGF and its receptor EGFR." (PMID 37696392, 2024). "PPV, including ORFV, lack an EGF-like gene and might rely on the WHR, which involves EGF induction and keratinocyte hyperplasia, for successful infection." (PMID 39958991, 2024). "One might argue that EGF has only minor functions in septic events, but EGF secretion resulted in reduced mortality in an infection model." (PMID 38046264, 2023). "Considering the parameters with the largest effects on the posterior probability of recurrent infection (i.e., IL-6, PCR CT, EGF, IL-8), bacterial burden and type 2 immunity clearly emerged as positive predictors and type 17 immunity as a negative predictor of recurrent CDI." (PMID 36975808, 2023). "The possibility of an intraamniotic infection effect on EGF concentrations was also analyzed." (PMID 35328399, 2022). "In addition, recent studies reported that infection of HUVECs by live B. bacilliformis induced host cell secretion of epidermal growth factor (EGF)." (PMID 35379004, 2022). "We hypothesize that bradykinin and EGF treatments increase infection by inducing filopodia, which results in increased viral binding." (PMID 35746622, 2022). "In addition, the quantity of EGF released in response to infection by strains LSS100 and LSS500 (overexpressing rGroEL) was significantly higher than that elicited by strain LSS001 (harboring the corresponding vector) (P < 0.05)." (PMID 32302357, 2020). "During work exploring the molecular basis for Bb-induced pathological angiogenesis, we determined that a 24-h infection by the bacterium resulted in a significant increase in expression and secretion of epidermal growth factor (EGF) into the culture medium as compared to uninfected control cells." (PMID 32302357, 2020). "In summary, we have discovered a potentially novel strategy whereby Bb could enhance proliferation and production of additional VEC hosts by inducing synthesis of EGF during infection." (PMID 32302357, 2020). "Results of the ELISA revealed significant increases in EGF production (P <0.01) in response to infections by all three Bb strains compared to mock-infected controls, with concentrations ranging from ~3 pg EGF / ml (strain LSS001) to 5 pg EGF / ml (strains LSS100 and LSS500)." (PMID 32302357, 2020). "Secretion of EGF by HUVECs in response to infection by Bb made us curious whether the reaction was due to an active infection or simply arose through bacterial interactions with the host cell." (PMID 32302357, 2020). "Killed bacteria or lysates of various Bb strains did not cause EGF production, suggesting that an active infection was necessary for the response." (PMID 32302357, 2020). "This EGF-dependent modulation of HBV internalization occurred before 24 h of post-infection." (PMID 32873852, 2020).
infection (continued). "One month after infection, EGF and TGFβ1 were expressed in all hamsters with inverse ratio." (PMID 30333964, 2018). "In the present study, we identified a putative EGFR-like kinase in N. caninum, which could be activated in tachyzoites by infection or treatment with rNcMIC3 [containing four epidermal growth factor (EGF) domains] or human EGF." (PMID 29075245, 2017). "EGF is one of the most abundant growth factors found in the milk and plays important roles in neonatal intestinal development to protect neonates against pathogens infection." (PMID 28164139, 2017). "The study sought to establish whether the infection of HGEC with live P. gingivalis would affect the mRNA expression of various genes potentially implicated in EGF signaling, mainly SOCS-3, IRF-1, EGF, EFGR, and STAT-3." (PMID 28748038, 2017). "The infection rate was higher in the EGF group (42.86% versus 0, Chi-square test, p = 0.025)." (PMID 29234410, 2017). "An increase in both phosphorylated p42/44 and p38 compared to control cells could be observed during infection and by treatment with EGF which acted as a positive control." (PMID 27002636, 2016). "We observed that PilC2-mediated infection did not alter the motility response to EGF, neither for cells associated with bacteria nor for cells devoid of attached meningococci." (PMID 19718432, 2009). "hPIV3 infection sustained the phosphorylation of these two translation factors at late time points, but showed no increase at the peak of stimulation, i.e. 30 min after adding EGF to the cells." (PMID 19806178, 2009). "We report that either hPIV3 infection or transient expression of hPIV3-C both increase cellular response to EGF, as assessed by Elk1 transactivation and phosphorylation levels of ERK1/2, 40S ribosomal subunit protein S6 and translation initiation factor 4E (eIF4E)." (PMID 19806178, 2009). "Like hPIV3-C alone, hPIV3 infection enhanced Elk1 activity upon EGF stimulation." (PMID 19806178, 2009). "Thus, our findings show that hPIV3-C not only inhibits the antiviral response but also stimulates cellular response to EGF, which benefits virus replication and induces an excessive inflammation of airways during infection." (PMID 19806178, 2009). "We further analysed the response of ME180 cells to EGF during infection with meningococci expressing constitutively PilC1 (Nm604a) or PilC2 (Nm910f), by monitoring cell motility for 30 minutes just prior to, or just following, addition of EGF to the cells." (PMID 19718432, 2009). "Early study of the proinflammatory response to Chlamydia also indicated that infection also induces production of fibrosis-associated cytokines such as IL-6, IL-11, and IL-17, as well as an extensive portfolio of fibrosis-associated growth factors (e.g. VEGF, CTGF, EGF)." (PMID 37265500, 2023). "In particular, due to the well-documented roles of EGF proteins in cell growth, proliferation, repair, or remodeling, as well as infection control, it is likely that the EGF domains in Is86 proteins may serve critical roles in Ixodes biology and infection." (PMID 33731754, 2021). "Interestingly, p65 and ERK1/2 phosphorylation decrements were related to the inhibitory ability of these pathotypes, since co-stimulation experiments showed that EPEC/EHEC prevents TNF-α-induced p65 phosphorylation and EGF-induced ERK1/2 phosphorylation post-infection." (PMID 27774437, 2016). "On the other hand, animals receiving the EGF-free F4 gel showed less infection which might be due to the higher percentage of chitosan; EGF especially might be reacting with polyelectrolytes and thus further increasing the amount of available chitosan, fortifying the antibacterial properties." (PMID 25110681, 2014).
infection (continued). "Infection with human cytomegalovirus (HCMV) has been associated with impaired differentiation of cytotrophoblasts down the invasive pathway, specifically dysregulating the response to mitogens including epidermal growth factor (EGF) and hepatocyte growth factor (HGF)." (PMID 23116176, 2012). "Similarly, depletion of EGF from the serum also robustly reduced infection levels." (PMID 22346752, 2012). "Vesicular systems deliver growth factors (e.g., EGF and TGF-β) and antimicrobial agents to promote tissue repair and reduce infection risks." (PMID 40277680, 2025). "This infection enhances ACLY S455phosphorylation and lipid droplet formation, with evidence suggesting dependency onVGF, the VACV homolog of cellular EGF." (PMID 39475274, 2024). "Per hsa-miR-155-5p is a regulator of the pro-inflammatory precursor mediators nuclear factor kappa-B cell (NF-KB), epidermal growth factor (EGF), and others, so hsa-miR-155-5p would be connected to both HCC and CHCV infection." (PMID 36834570, 2023). "Lower age, PCR CT, IL-6, IL-8, and IL-17A and higher IL-16, EGF, and CCL-5 appeared to provide the best univariate class separation for recurrent infection (versus recurrence-free survival and death)." (PMID 36975808, 2023). "Parasitic infection of colitic mice resulted in upregulation of mucosal AREG, EGF, FGF-2, and IGFBP-3 in the intestine of the host and better adaptation (infectivity)." (PMID 36836678, 2023). "In vivo, it is known that elevated EGF levels in the ERM compartment (as, for instance, occurring upon tooth movement, infection or trauma) activates ERM cell proliferation." (PMID 35217915, 2022). "The gene encoding SOCS4 has been shown to be widely expressed, and induced by epidermal growth factor (EGF), while infection can indirectly increase SOCS4 protein levels." (PMID 35204004, 2022). "A few cytokines and chemokines of importance for tissue repair was also resistant to cleavage, including EGF, PDGF-B, BMP-2 and 14, indicating that these are stabilized to resist degradation to enable repair of damaged tissues after an inflammation/infection." (PMID 31963828, 2020). "Significant downregulation of EGF expression was observed at 12 h in both pH1N1-alone (p = 0.0003) and pH1N1-MRSA (p = 0.0002) infection and was resolved by 24 h." (PMID 33202895, 2020). "Although the acute infection leads to activation of multiple paracrine growth factors (TGF-β1, EGF, FGF etc.), we identify LIF as a key player in the maintenance of stemness in tubal organoids." (PMID 30886143, 2019). "The reduced responsiveness of EGR1 to EGF stimulation in infected cells likely reflects diminished EGFR levels and signaling in the context of infection beginning at 24 hpi." (PMID 31725811, 2019). "In this study, each woman exhibited a unique immune response with raised IL‐1RA, IP‐10, EGF and RANTES expression and neutrophil numbers during the acute infection phase." (PMID 31709049, 2019). "Supplying the medium with EGF did not only abolish diminished ERK phosphorylation after ADAM17 depletion, but as well restored infection in ADAM17-depleted cells." (PMID 31107240, 2019). "EGFR is a proviral factor in HPV16 entry (A) and soluble EGF relieves the effect of ADAM17 depletion on the phosphorylation status of ERK1/2 (B, C), HPV16 PsVs infection rate (D) and HPV16-CD151 proximity (E, F)." (PMID 31107240, 2019). "In this study, each woman exhibited a unique immune response, but they collectively diverged from healthy controls with raised IL‐1RA, IP‐10, EGF and RANTES expression and neutrophil numbers during the acute infection phase." (PMID 31709049, 2019). "Expression levels lower than the constitutive gene were found for the PDGF, EGF, TGFβ1, and FGF before infection, and these basal levels were used for the calculation of ΔΔCT." (PMID 30333964, 2018).